ABCG2 (ATP binding cassette subfamily G member 2 (JR blood group))
Diseases named in the same sentence as ABCG2 in open-access papers (continued):
Sharing a sentence is not in itself a finding about the gene and the disease.
tumor (continued). "Conceivably, ABCG2 might also have a biological role in tumor progression by affecting tumor stem cells." (PMID 29186899, 2017). "CSCs are characterized by their tumor forming ability and expression of high levels of ATP-binding cassette drug transporters (ABCG2), cell adhesion molecules (CD44), and anchorage independent cell survival proteins (Cyclin D1), which are collectively responsible for chemo-resistance." (PMID 28536422, 2017). "Interestingly, the expression of 84 stem cell genes within different GBM regions reveals that the invasive region has the highest ALDH1A1 and ABCG2 expression as compared to other tumour regions." (PMID 29156557, 2017). "Two studies compared the expression of ABCG2 mRNA in normal colon tissue and tumor tissue." (PMID 28880238, 2017). "Since verteporfin can inhibit ABCG2 transcription, we asked whether verteporfin could help doxorubicin inhibit tumor cell growth." (PMID 27911857, 2017). "Each of the CpGs in the ABCB1 and ABCG2 promoters was methylated in ≥ 75% of the tumor tissues." (PMID 27689338, 2016). "Together, these data suggest that while ABCG2 function promotes stem cell marker expression and self-renewal, other key features of stem-like tumor cells may be independently regulated." (PMID 27456282, 2016). "In addition, positive correlations were found between MIB-1 and the methylation status of CpG6 and CpG7 in the ABCG2 promoter in the tumor-distant tissues." (PMID 27689338, 2016). "In case of ABCG2, all tumor tissues except one showed an average methylation status < 25%." (PMID 27689338, 2016). "In addition, a correlation was found between the methylation status of CpG6 and CpG7 in the ABCG2 promoter in tumor-distant tissues and MIB-1 (r = 0.556, p = 0.025 and r = 0.550, p = 0.027, respectively)." (PMID 27689338, 2016). "Facs analysis on tumor cells pooled from tumors derived from either treated or control animals, revealed decreased number of CD133+ and ABCG2+ BTICs in tumor from 4-HPR treated animals confirming in vivo the ability of fenretinide to target the MB stem component shown in vitro." (PMID 27367907, 2016). "We next asked whether forced expression of ABCG2, which results in an increased SP phenotype, was sufficient to promote tumor formation." (PMID 27456282, 2016). "However, ABCG2 is present not only in tumour cells, and its function in the development of MDR is a manifestation of the physiological role of this protein." (PMID 26578453, 2016). "In conclusion, HIF-2α, ABCG2 and Oct-4 mRNA and protein expression levels were significantly increased in the tumor tissues of the 5-Fu group; this may be a due to the tumor cells having resistance to 5-Fu." (PMID 25452783, 2015). "Therefore, the effective clinical concentration of gefitinib in the local tumour environment is presumably in the range of micromolar, suggesting that this drug is more likely to act as an ABCG2 inhibitor in vivo." (PMID 26536031, 2015). "However, at 7 days after the injection, the tumor volume increased by a greater extent in mice injected with SW480/ABCG2 cells compared to mice injected with SW480 cells." (PMID 26149077, 2015). "Finally, the effects of miR-222 and ABCG2 on tumor growth and lung metastasis in vivo were evaluated." (PMID 26517090, 2015). "In tumor tissues, ABCG2 expression correlates with high Ki67 expression, a well-established marker of cell proliferation, suggesting that ABCG2 may regulate the proliferation of tumor cells." (PMID 26064420, 2015). "Furthermore, we checked the anti-tumor effect on xenograft model using cells with either low or high expression of ABCG2 cell in vivo." (PMID 26149077, 2015). "Naturally, studies on clones growth rate, resistance to indomethacin and ABCG2 proteins expression level were respectively carried out, which were together to explore whether there were apparent tumor heterogeneity existing between the two types of clones." (PMID 26149707, 2015).
tumor (continued). "However, the H460 tumor xenografts exhibited a more dramatic reduction when compared to H460/MX20 xenografts due to lack of ABCG2 expression in H460 tumors results in increased concentration of topotecan when compared to H460/MX20 tumors." (PMID 26515463, 2015). "Moreover, miR-222 mimics and ABCG2 siRNA significantly inhibited tumor growth and lung metastasis in vivo." (PMID 26517090, 2015). "Moreover, the fact that ABCG2 inhibitor Ko143 is able to reduce PpIX fluorescence heterogeneity in tumor cells suggests that ABCG2 is involved in the intra-tumor heterogeneity of ALA-PpIX." (PMID 26516850, 2015). "Elevated expression of ABCB1, ABCG2, and ABCCs mRNA in pancreatic adenocarcinomas compared to normal pancreas has been reported, but correlation with clinical aggressiveness of the tumor remains controversial." (PMID 24883056, 2014). "It was therefore concluded that V-BCRPi could more efficiently downregulate BCRP/ABCG2 mRNA in tumor histiocytes." (PMID 25076217, 2014). "It is suggested that gefitinib might reverse tumor resistance to SN-38 mediated by ABCG2 by blocking the drug efflux function and might be beneficial in humans to regulate the oral bioavailability of poorly absorbed drugs such as irinotecan." (PMID 25268163, 2014). "Furthermore, telatinib stimulated the ATPase activity and also in combination with DX, it decreased the ABCG2 overexpressing tumor size." (PMID 25191874, 2014). "We, therefore, assume that pharmacokinetics of olomoucine II will be affected by both ABCB1 and ABCG2 transport proteins, which might potentially result in limited accumulation of the compound in tumor tissues or lead to drug-drug interactions." (PMID 24116053, 2013). "We further examined whether the drug-efflux effect of BCRP/ABCG2 affects the anti-tumor effect of sorafenib in HCC cells." (PMID 24391798, 2013). "Again ABCG2 may be an effective target for the prevention of tumor metastasis and corresponding strategies targeting ABCG2 may help improve the metastatic behavior of HCC." (PMID 24194752, 2013). "ABCG-2 is thought to be a survival factor of SCs, ultimately driving tumor growth." (PMID 23687063, 2013). "This may be because ABCG2+ tumor-initiating cells gradually differentiated and turned into quiescence during the process of tumor growth." (PMID 24194752, 2013). "The transport capacity of ABCG2 for methotrexate, folic acid, mitoxantrone and topotecan can be enhanced under low pH conditions in tumor cell lines, such that at pH 5.5, the transport capacity of ABCG2 for drugs is five times higher than that of the normal conditions." (PMID 23984887, 2013). "Moreover, Hh signaling promotes multidrug resistance (MDR) by increasing transcription of ABC transporter proteins ABCB1 and ABCG2 in different tumor types, including PCa." (PMID 23880852, 2013). "Unexpectedly, when we measured topotecan pharmacokinetics in the ABCG2-positive tumor T1 we were unable to detect significant differences between the vehicle + topotecan-treated (green line) and Ko143+ topotecan-treated animals (red line) (P = 0.713, unpaired t-test)." (PMID 23028879, 2012). "Treatments combining the administration of ABCG2 inhibitors and conventional chemotherapy may prove effective in eradicating both the bulk and chemoresistant populations of a tumor, thereby reducing the likelihood of recurrence." (PMID 23144836, 2012). "Novel clinical interventions may be devised to help circumvent this ABCG2-mediated resistance by modulating the tumor microenvironment." (PMID 22778999, 2012). "The upregulation of ABCG2 observed above suggested that all of the tumor microenvironment conditions investigated may confer a more drug-resistant phenotype." (PMID 22778999, 2012). "The weight of tumor blocks was highest in ABCG2− cell group and lowest in ABCG2+ cell group." (PMID 22209971, 2012). "Tumor formation rate was lowest in ABCG2+ cell group (2/3) and was 100% (3/3) in other two groups." (PMID 22209971, 2012).
tumor (continued). "This two-pronged action may disrupt tumor ABCG2 function in a more profound and longer-lasting way than treatment with Ko143." (PMID 23028879, 2012). "Sustained SN38 release from EZN-2208 in the tumor stroma may counteract cellular ABCG2-mediated efflux and maintain a steep diffusion gradient towards the topoisomerase I target within the tumor cell nuclei." (PMID 23028879, 2012). "By using ABCG2-proficient tumors in ABCG2-deficient hosts, we ensured that the Ko143 effect was indeed tumor-specific and not due to drug clearance differences." (PMID 23028879, 2012). "ABCG2 also plays a critical role in hypoxic defense mechanisms within the tumor microenvironment." (PMID 22778999, 2012). "Cells obtained from the xenograft tumor tissues expressed ABCG2, CD243 (p-gp) and CD24." (PMID 22844424, 2012). "Taken together, the three adverse growth conditions in the tumor microenvironment tested were found to upregulate ABCG2 to mediate multidrug resistance, with the possible enhancing effect on preexisting MDR mechanism, and to give rise to a more malignant phenotype." (PMID 22778999, 2012). "When inoculated with 105 cells, tumor block could be seen after 12 days in ABCG2− cell group and 5–8F cell group and after 20 days in ABCG2+ cell group." (PMID 22209971, 2012). "The ABCG2-positive rate was 2.11%, which is similar to those in other tumor cells." (PMID 22209971, 2012). "In this study CD44, CD24, ABCG2, and EpCAM could be detected by flow cytometry in all the RB patient tumor samples." (PMID 22328825, 2012). "This piece of data is important because it suggests that tumor microenvironment could coordinately regulate ABCG2 with preexisting MDR mechanisms to attain a higher resistance level." (PMID 22778999, 2012). "Co-treatment with BCRP/ABCG2 inhibitors enhanced the anti-tumor activity of gefitinib." (PMID 21731744, 2011). "This might be due to the strong expression of the PPIX efflux transporter gene Abcg2 in C2 tumors and the C2 tumor cell line and could explain the dose-limiting side effects seen in the mice after PDT." (PMID 21738796, 2011). "In MDR tumour cells, various member of the ABC family of transport proteins can simultaneously be overexpressed: these include P-gp (ABCB1), breast cancer resistance protein (BCRP, ABCG2) and MDR associated protein 1 (MRP1, ABCC family)." (PMID 21269449, 2011). "In fact, ABCG2+ cells gave a bigger tumor mass than ABCG2- cells in immunodeficient mice." (PMID 21203549, 2010). "Furthermore, they identified tumor-initiating cells in human melanoma by the expression of ABCG2 which is coexpressed with CD133." (PMID 20459772, 2010). "Endogenous ABCG2 expression in tumor cells may contribute to intrinsic drug resistance." (PMID 41541684, 2026). "However, in the context of tumor cells, ABCG2 often exhibits unfavorable effects." (PMID 41541684, 2026). "Therefore, we speculated that p38 might contribute to the reduced sensitivity of tumor cells to a variety of chemotherapeutic drugs through ABCG2." (PMID 41541684, 2026). "This heterogeneity underscores the complexity of ABCG2 function and suggests that the combined therapeutic strategies involving p38 inhibitors may need to be tailored based on the specific regulatory network of different tumor types." (PMID 41541684, 2026). "Additionally, ABCG2 expression is strongly associated with endothelial cell infiltration, suggesting that ABCG2 may contribute to enhanced tumor invasiveness." (PMID 40282409, 2025). "Therefore, we conducted a series of experiments to figure out whether the HBO treatment affects tumor chemotherapy sensitivity and proliferation by inhibiting HIF1α/HIF2α-ABCG2." (PMID 40370575, 2025). "Therefore, high ABCG2 expression might correlate with a higher proportion of CSCs in the tumor, potentially leading to increased resistance to radiotherapy." (PMID 38542090, 2024).
tumor (continued). "Although the direct role of ABCG2 in tumor angiogenesis is less clear, the protein’s presence in endothelial cells suggests it might influence the tumor microenvironment and the development of new blood vessels, which are essential for tumor growth and metastasis." (PMID 38542090, 2024). "They postulate that downregulation of ABCG2 may enhance the accumulation of protoporphyrins in the tumour cell, resulting in increased generation of heme, a cofactor for isoform I of nitric oxide synthases, and sustainable production of precancerous nitric oxide during malignancy." (PMID 37445716, 2023). "Furthermore, we explored the effect of ABCG2 on MHI-148 efflux in tumor-bearing mice." (PMID 37064109, 2023). "In addition, some of the tumor cells overexpressed the ABCG2 that belongs to the ATP-binding cassette (ABC) transporter superfamily, which can pump chemotherapy drugs, such as paclitaxel, cyclophosphamide, and gemcitabine, out of tumor cells, thereby making the cells resistant to chemotherapy." (PMID 36553542, 2022). "Therefore, the therapeutic effect of MLN7243 may be attenuated in patients with high tumor ABCG2 expression." (PMID 34336849, 2021). "Moreover, overexpression of ABCG2 has been observed in a variety of tumor tissues, which could potentially indicate the probability of chemotherapy resistance." (PMID 33509236, 2021). "Moreover, ABCG2, which is known to be the crucial transporter associated with stem cells and SP, was found to have reduced levels of mRNA and protein in both STIL-silenced HT29 cells and xenograft tumor tissue." (PMID 34485108, 2021). "ABCG2 transcript in HNCs was highly expressed in undifferentiated (grade 4) tumor tissues in contrast to normal head and neck tissues, while ABCG2 levels negatively correlated with patient prognosis, implying that ABCG2 could serve as a prognostic marker for HNCs in clinics." (PMID 32957726, 2020). "Therefore, tumor ABCG2 level may serve as a predictor for irinotecan resistance during long-term treatment." (PMID 33692943, 2020). "To test whether in the olaparib-resistant cohort there is a link between the increase in proportion of MSCC/EMT-like tumours and the up-regulation of the P-gp Abcb1a, Abcb1b and Abcg2, we compared their expression in olaparib-naïve and olaparib-resistant tumours." (PMID 31080552, 2019). "The limited data suggest that ABCG2 tumor cell expression might not be associated with patient prognosis." (PMID 28880238, 2017). "Low levels of ABCG2 that was detected in resections of primary tumors therefore can be considered as part of the dedifferentiation process leading to low E-cadherin levels and loosened tight junction interactions facilitating cellular migration that is necessary for tumor progression." (PMID 28340578, 2017). "Statistical analyses revealed that in tumor tissues the average promoter methylation status of ABCB1 (across the seven CpGs investigated) significantly correlated with the average promoter methylation status of ABCG2 (across the eight CpGs investigated) (r = 0.621; p = 0.010)." (PMID 27689338, 2016). "Observations from IHC with mAb BXP-21 of the 9 FFPE CRC tissue samples revealed three distinguishable ABCG2 expression patterns of the tumor cells, namely basolateral membrane, apical membrane and cytoplasmic, which could be detected separately or in combination." (PMID 27257141, 2016). "Additionally it was found that tumor-initiating cells in human melanoma could be identified by the expression of ABCG2 coexpressed with CD133." (PMID 26649310, 2015). "It should be noted that we could not elucidate the molecular mechanism by which ENPP1 induces upregulation of ABCG2 at the mRNA level or the role of ENPP1 in the acquisition of tumour seeding ability; therefore, additional investigations of ENNP1 functions are required." (PMID 26065921, 2015). "Moreover, miR-222 mimics and ABCG2 siRNA inhibited tumor growth and lung metastasis in vivo." (PMID 26517090, 2015).
tumor (continued). "For determination of the ABCG2 promoter methylation a novel pyrosequencing assay was established by our group to analyze three CpG sites that have been previously determined in other tumor entities using methylation specific quantitative PCR and bisulfite genomic sequencing." (PMID 24380367, 2013). "Hence, when combining an ABCG2 inhibitor with topotecan, it may be difficult to distinguish tumor-specific ABCG2 inhibition versus increased drug exposure due to reduced excretion." (PMID 23028879, 2012). "Such prolonged tumor-specific drug delivery may help to overcome ABCG2-mediated resistance." (PMID 23028879, 2012). "Of note, the selection of tumour initiating cells by this in vivo assay resulted in enrichment of these stem cell markers, over baseline levels in vitro, where differences were 11-fold, 80-fold, 44-fold and 140-fold for ABCG2, Nanog, Notch1 and SOX2 expression, respectively (p<0.05)." (PMID 23226356, 2012). "We, therefore, hypothesized that LPA decreases Taxol-induced accumulation of the cells in G2/M by stimulating Taxol efflux through ABCB1 (multidrug resistance gene 1), p-glycoprotein (ABCC1) or ABCG2, since these transporters account for a major portion of drug resistance in human tumor cells." (PMID 21647386, 2011). "However, CXCR6-expressing cells were more aggressive for tumor formation than ABCG2-expressing cells, suggesting that the subpopulation CXCR6+/ABCG2+ cells may be the most potent MCSCs." (PMID 21203549, 2010). "To verify the regulatory role of p38 in ABCG2 function, we employed the p38 inhibitor BIRB 796 to assess its impact on the sensitivity of tumor cells to various chemotherapeutic drugs, including MIT, DOX, and TP, all of which are ABCG2 substrates." (PMID 41541684, 2026). "For TMZ specifically, the inhibition of ABCB1, ABCG2, ABCE1, ABCC1, and ABCB5 has seen significant decreases in either GBM tumor volume/weight by (~40–90% reduction), or significant increases in median survival (~1.3- to 5-fold increase)." (PMID 39861164, 2025). "These tumor spheres exhibited high RNA levels of CSC markers CD26, CD44, and ABCG2 as well as hypoxia adaptation markers ABCG2, ALDH1, and HIFs." (PMID 40149313, 2025). "CKS1B knockdown significantly reduced the self-renewal capacity and number of CSCs, as evidenced by in vitro tumor sphere formation, increased CD44+CD24+/CD133+ cell populations, and decreased expression of CSCs markers (ABCG2, C-MYC, ALDH1, BMI-1)." (PMID 39897042, 2025). "Upregulation of miR-142-3p suppressed growth of CRC cells and xenograft tumor by downregulating CD133, ABCG2, and Lgr5, CDK4, and CTNNB1." (PMID 40868120, 2025). "The viability of tumor specimens was analyzed by MTT assay and an Image Analysis System, and the expression of ABCB1, ABCG2, and ABCC1 proteins in specimens was synchronously detected via western blot assays." (PMID 41328326, 2025). "In many cases, CSCs express specific surface markers distinct from those of the surrounding tumor cells, including the ABC transporters ABCB1 and/or ABCG2." (PMID 40508176, 2025). "Hyper‐expression of ABCB1, ABCG2, or ABCC1 has been documented in clinical tumor specimens to mediate MDR and poor prognosis in patients bearing malignancies in breast, liver, blood, colon, and lung." (PMID 41328326, 2025). "Many molecules have been proposed as markers (ALDH1a1, ABCG2, CD44, CD133, CD271, NANOG), but they are also found in non-tumor stem cells and normal melanocytes." (PMID 40806546, 2025). "This is achieved by inhibiting the efflux of ABCG2-dependent drugs and elevating intracellular DOX concentration via miR-519c, subsequently inhibiting tumor growth and achieving desirable therapeutic effects in HCC animal studies." (PMID 38735927, 2024). "The subfamily ABCB1/MDR1/P-glycoprotein, ABCC1/MRP1, and ABCG2/BCRP are the most extensively studied and considered as prime factors for the induction of MDR in tumor cells." (PMID 38611964, 2024).